ENSG00000236140 (novel transcript)
Gene: Long non-coding RNA gene on chromosome 1 (145,216,552 to 145,287,964, reverse strand). Ensembl gene ENSG00000236140.
Gene Ontology:
Molecular function: triplet codon-amino acid adaptor activity
Biological process: translation